MICALL2 (MICAL like 2)
Diseases named in the same sentence as MICALL2 in open-access papers:
MICALL2 is named in the same sentence as 18 diseases in open-access papers, as found by Europe PMC text mining. Sharing a sentence is not in itself a finding about the gene and the disease. The quoted sentences say what the papers report.
ovarian carcinoma (9 papers, 2018 to 2025). A malignant neoplasm originating from the surface ovarian epithelium. "We showed by bioinformatics analysis that MICALL2 expression was significantly higher in tissues of advanced-stage ovarian cancer and associated with poor overall survival of patients." (PMID 38203692, 2023). "Initially, we explored the association between MICALL2 expression and immune-cell infiltration in ovarian cancer through single-sample GSEA." (PMID 38203692, 2023). "To confirm the role of MICALL2 in the regulation of cell migration and invasion, we performed MICALL2 loss-of-function assays in ovarian cancer cells." (PMID 38203692, 2023). "Similarly, the findings of the present study demonstrated that upregulation of MICALL2 was associated with malignant phenotypes in patients with ovarian cancer, probably through matrix degradation and immune infiltration pathways." (PMID 38203692, 2023). "Overall, these data indicated that MICALL2 expression is upregulated in ovarian cancer, and this increased expression may be associated with poor prognosis among patients with ovarian cancer." (PMID 38203692, 2023). "A possible explanation for this observation is that the inhibitory effects of some EGFR downstream effectors caused by the silencing of MICALL2 may be counteracted by compensatory effects in ovarian cancer cells." (PMID 38203692, 2023). "In addition, high MICALL2 expression was associated with poor overall survival of patients with grade 3–4 ovarian cancer and poor progression-free survival of patients with stage T3–T4 ovarian cancer." (PMID 38203692, 2023). "Next, the effects of MICALL2 depletion on ovarian cancer cell migration and invasion were evaluated by wound healing and transwell assays." (PMID 38203692, 2023). "Collectively, our results indicated that MICALL2 participated in the process of immune infiltration and invasion by ovarian cancer cells." (PMID 38203692, 2023). "We further compared MICALL2 expression between ovarian cancer tissue and normal tissue using data from the GSE52037 dataset, obtaining similar results." (PMID 38203692, 2023). "In the present study, we used bioinformatics analysis and immunohistochemical assays to investigate the expression of MICALL2 in ovarian cancer tissue samples." (PMID 38203692, 2023). "Analysis of the GSE6008 dataset showed that MICALL2 expression was significantly higher in mucinous ovarian, serous, clear cell, and endometrioid types of ovarian cancer than in normal ovarian mucosa." (PMID 38203692, 2023). "It was found that MICALL2-overexpressing ovarian cancer cells attract multiple immune cells into the tumor." (PMID 38203692, 2023). "In conclusion, the findings of this study propose a new mechanism through which MICALL2 participates in the process of immune infiltration and matrix degradation by ovarian cancer cells." (PMID 38203692, 2023). "In ovarian cancer cells, silencing of MICALL2 greatly suppressed Rac1 activation, whereas MICALL2 overexpression exerted the opposite effect." (PMID 38203692, 2023). "Thereafter, a number of regulated proteins in the downstream signaling pathway of EGFR were identified by examining the mechanism through which MICALL2 induced MMP9 transcription in ovarian cancer cells." (PMID 38203692, 2023). "The aim of this study was to investigate the potential role of one member of MICALs, i.e., MICALL2, in the invasion and function of ovarian cancer cells." (PMID 38203692, 2023). "Further investigation is warranted to verify these results and to accurately understand the relationship between MICALL2 and immune infiltration within the microenvironment of ovarian cancer." (PMID 38203692, 2023). "For example, MICALL2-targeting-shRNA dramatically suppressed the proliferation, migration and invasion of ovarian cancer cells or gastric cancer cells." (PMID 36307841, 2022).
ovarian carcinoma (continued). "In accordance with the pan-cancer analysis, prior studies showed that MICALL2 is highly expressed in ovarian cancer, gastric cancer, and lung cancer demonstrated by western blot or immunohistochemical staining 17-19." (PMID 35281853, 2022). "Therefore, the results demonstrated that MICALL2 was closely correlated with the regulation of T-cell exhaustion in ovarian cancer." (PMID 38203692, 2023). "Further advances in our understanding of the function of MICALL2 may have important implications for the treatment of ovarian cancer." (PMID 38203692, 2023). "Based on these findings, we hypothesize that the functions of MICALL2 in promoting ovarian cancer cell invasion might be mediated by the stabilization of EGFR expression and, consequently, the activation of EGFR downstream signal pathways." (PMID 38203692, 2023). "Therefore, we further investigated immune infiltration and the matrix-degradation pathway to better understand the function of MICALL2 in ovarian cancer." (PMID 38203692, 2023). "Overall, our clinical and in vitro data supported that MICALL2 may participate in the process of immune reaction and promote ovarian cancer cell invasion via the EGFR pathway." (PMID 38203692, 2023). "In addition, the results regarding YAP phosphorylation status after the knockdown of MICALL2 in the two ovarian cancer cells were inconsistent." (PMID 38203692, 2023). "Subsequently, we evaluated the role of MICALL2 in ovarian cancer carcinogenesis." (PMID 38203692, 2023). "Therefore, we next tested whether MICALL2 modulates the expression of MMP9 in ovarian cancer cells SKOV3." (PMID 38203692, 2023). "We sought to explore whether MICALL2 affects the expression of MMPs in ovarian cancer cells." (PMID 38203692, 2023). "However, to the best of our knowledge, the effects of MICALL2 on ovarian cancer cell invasion and the mechanisms responsible for this association remain unclear." (PMID 38203692, 2023). "Although MICALL2 stabilized EGFR expression, it only stabilized the activation of its downstream AKT–mTOR signaling pathway in ovarian cancer cells." (PMID 38203692, 2023). "Additionally, it was observed that the silencing of MICALL2 prevented the activation of canonical wnt/beta-catenin signaling and induced mesenchymal–epithelial transition (MET) in ovarian cancer cells." (PMID 38203692, 2023). "Moreover, we identified a novel link between MICALL2 and MMP9 in the regulation of invadopodia formation and the invasion of ovarian cancer cells." (PMID 38203692, 2023). "To investigate whether our in vitro experimental results are consistent with the pathogenesis of ovarian cancer, we examined the expression of MICALL2 and MMP9 in ovarian cancer and adjacent tissues using a microarray (30 paired cases)." (PMID 38203692, 2023). "Consequently, we hypothesized that MICALL2 may promote EGFR-signaling activation and MMP9 expression in ovarian cancer cells." (PMID 38203692, 2023).
breast carcinoma (3 papers, 2019 to 2022). "High levels of MICALL2 expression have been reported in a range of malignancies including ovarian, gastric, and breast cancers, consistent with the high levels of variability observed for this gene." (PMID 36290165, 2022).
colon adenocarcinoma (2 papers, 2022 to 2023). "In a previous study, we suggested that MICALL2 is highly expressed in colon adenocarcinoma and could be a promising biomarker for determining the poor prognosis of patients with this disease." (PMID 38203692, 2023).
colorectal cancer (2 papers, 2020 to 2022). A primary or metastatic malignant neoplasm that affects the colon or rectum. "Collectively, these results suggested that MICALL2 was crucial in the tumorigenesis of colorectal cancer." (PMID 36307841, 2022). "As a substrate of ubiquitinase TRIM21, MICALL2 enhances the growth and migration of colorectal cancer cells and activates the Wnt/β-catenin signaling pathway." (PMID 36307841, 2022). "Functional studies confirmed that MICALL2 promoted colorectal cancer cell growth and migration via the Wnt/β-catenin signaling pathway." (PMID 36307841, 2022). "And, we also discovered the potential oncogenic role of MICALL2 on colorectal cancer cell tumorigenicity by activating the Wnt/β-catenin signaling cascade." (PMID 36307841, 2022). "Then, we performed IHC to evaluate the potential association between MICALL2 and TRIM21 in the serial sections of human colorectal cancer tissue microarrays." (PMID 36307841, 2022). "The expression levels of MICALL2 were up-regulated in colorectal cancer tissues by using RNAseq data from The Cancer Genome Atlas (TCGA), and Kaplan–Meier survival curve analysis demonstrated that CRC patients with higher MICALL2 protein expression had poorer overall survival rate." (PMID 36307841, 2022). "Furthermore, IHC analysis revealed that the expressions of MICALL2 in colorectal cancer tissues were significantly increased compared with adjacent non-tumor colorectal tissues." (PMID 36307841, 2022). "However, the biological function of MICALL2, its role in cancer signal transduction, and its clinical significance in human colorectal cancer are still remained elusive." (PMID 36307841, 2022). "Our findings shed light on the biological role of MICALL2 in the process of colorectal cancer and suggest that MICALL2 could be a potential target for colorectal cancer therapy." (PMID 36307841, 2022). "Taken together, we highlighted the vital role of MICALL2, as an E3 ubiquitinase TRIM21 substrate, in colorectal cancer progression by activating Wnt/β-catenin signaling pathway." (PMID 36307841, 2022). "Then, the interaction between endogenous MICALL2 and TRIM21 in colorectal cancer cells was validated in the co-immunoprecipitation experiment." (PMID 36307841, 2022). "When preparing this manuscript, we learned that another group identified the higher expression of MICALL2 in CRC, however, biological role in colorectal cancer (CRC) remain elusive." (PMID 36307841, 2022). "And, in colorectal cancer tissues, there is a negative correlation of MICALL2 expression level with TRIM21, which promotes the ubiquitination and degradation of MICALL2." (PMID 36307841, 2022). "We found that both mRNA and protein levels of MICALL2 are up-regulated in colorectal cancer tissues compared with non-tumor tissues and that its overexpression is closely correlated with poor prognosis." (PMID 36307841, 2022). "In colorectal cancer cells, TRIM21 interacts with MICALL2 and down-regulates it synergistically via ubiquitination and degradation, and negatively regulates the activities of MICALL2 in CRC." (PMID 36307841, 2022). "Furthermore, in those colorectal cancer samples, a negative correlation between MICALL2 and TRIM21 proteins was observed (r = − 0.30, P < 0.01)." (PMID 36307841, 2022).
bladder cancer (1 paper, 2022). "We found that only DYM and MICALL2 genes affected the clinical outcome of bladder cancer." (PMID 35769470, 2022). "Therefore, the roles of DYM and MICALL2 in bladder cancer were investigated in further analyses." (PMID 35769470, 2022).
glioma (1 paper, 2020). A benign or malignant brain and spinal cord tumor that arises from glial cells (astrocytes, oligodendrocytes, ependymal cells). "Of these, ten genes (CTSZ, EFEMP2, ITGA5, KDELR2, MDK, MICALL2, MAP 2 K3, PLAUR, SERPINE1 and SOCS3) can potentially classify patients with gliomas into different risk groups." (PMID 32878880, 2020).
cancer (8 papers, 2018 to 2023). A tumor composed of atypical neoplastic, often pleomorphic cells that invade other tissues. "To explore the role of MICALL2 in immunoregulation, we firstly performed a pan-cancer co-expression analysis on the immunoregulatory genes encoding MHC, immunosuppression, immune activation, chemokine receptors, and chemokines proteins." (PMID 35281853, 2022). "To date, this is the first report to demonstrate that MICALL2 could be a prognostic biomarker associating with cancer progression, inflammatory, and immune signatures of KIRC." (PMID 35281853, 2022). "Furthermore, MICALL2 may involve in the regulation of signaling pathways associated with cancer progression, such as JAK-STAT signaling pathway, MAPK signaling pathway, and VEGF signaling pathway." (PMID 35281853, 2022). "As shown in the flow process diagram, we evaluated MICALL2 differential expressions across 33 cancer types and their corresponding normal tissues." (PMID 35281853, 2022). "UCSC Xena database was introduced to analyze the differential expression of MICALL2 across 33 cancer types and their corresponding normal tissues." (PMID 35281853, 2022). "Here we reported for the first time that MICALL2 is highly expressed in multiple cancer types and can serve as an independent predictor for poor prognosis in KIRC patients." (PMID 35281853, 2022). "Therefore, in recent years, more attention has been gradually attracted from its biological function to the effects of MICALL2 on cancer progression." (PMID 35281853, 2022). "We next preliminarily explored the role of MICALL2 expression in pan-cancers." (PMID 35281853, 2022). "Furthermore, MICALL2 can regulate the signaling pathways related to tumor immunity, tumor progression, and cancer metabolism." (PMID 35281853, 2022). "Then we conducted the preliminary exploration on the role of MICALL2 expression in pan-cancers." (PMID 35281853, 2022). "In this study, we analyzed the expressions of MICALL2 across 33 cancer types, finding that compared with the corresponding normal tissues, MICALL2 was highly expressed in 16 types of cancers including KIRC while MICALL2 levels were downregulated in PCPG tissues." (PMID 35281853, 2022). "However, it remains poorly understood whether MICALL2 can be developed as an ideal biomarker to predict cancer progression and patient prognosis." (PMID 35281853, 2022). "Furthermore, TRIM21 knockdown partially reversed the cancer-promoting effects of MICALL2 in CRC cells, suggesting that TRIM21 may be a crucial regulatory molecule for MICALL-mediated oncogenic signaling in CRC." (PMID 36307841, 2022). "It was found that eight proteins (ADD2, DEF6, DOK3, ENO2, FMNL1, MICALL2, PARVG, and PSTPIP1) in KIRC cancer were more highly expressed in tumor tissues (100%), compared with normal tissues." (PMID 36428765, 2022).
tumor (8 papers, 2019 to 2023). "Consistently, MICALL2 involved in the regulation of signaling pathways associated with tumor immunity, tumor progression, and impaired metabolic activities." (PMID 35281853, 2022). "In this study, we found that the expression level of MICALL2 is up-regulated in human CRC tissues when compared with matched non-tumor tissues, and that high expression of MICALL2 is associated with poor prognosis of CRC patients." (PMID 36307841, 2022). "To determine the cellular functions of MICALL2 in promoting tumor invasion, we tested whether the expression of MICALL2 was associated with an increased ability to degrade ECM." (PMID 38203692, 2023). "Immunohistochemistry results indicated that MICALL2 was highly expressed in tumor tissues compared with matched paracancerous tissues." (PMID 38203692, 2023). "A growing interest has been attracted from the biological function of MICALL2 to its effects on tumor progression." (PMID 35281853, 2022). "And, in vitro and in vivo studies demonstrated that MICALL2 promoted tumor cell growth and migration via activating Wnt/β-catenin signaling pathway." (PMID 36307841, 2022). "For the first time, this present study integratedly assessed the effects of MICALL2 in patient prognosis, tumor progression, inflammatory, and immune signatures of KIRC." (PMID 35281853, 2022). "We found that MICALL2 expression was significantly higher in tumor tissues versus normal tissues." (PMID 38203692, 2023). "Moreover, enrichment analyses showed that MICALL2 was involved in the tumor-related matrix degradation pathway." (PMID 38203692, 2023). "Based on the significant results, we hypothesized that MICALL2 expression had close relation to patient prognosis, tumor progression, and immune infiltration in KIRC which was mainly investigated in the follow-up bioinformatics analyses." (PMID 35281853, 2022). "Furthermore, MTT assay, colony formation assay, wound-healing assays and xenograft tumor models were performed to demonstrate the functions of MICALL2 in CRC." (PMID 36307841, 2022). "Therefore, our findings revealed that MICALL2 expression was positively correlated with tumor progression." (PMID 35281853, 2022). "Furthermore, tumor xenograft experiments revealed that MICALL2 overexpression promoted the growth of HCT116 tumors." (PMID 36307841, 2022). "Based on the significant results, we hypothesized that MICALL2 expression had close relation to patient prognosis, immune infiltration, and tumor progression in kidney renal clear cell carcinoma (KIRC) which was mainly investigated in the follow-up bioinformatics analyses." (PMID 35281853, 2022). "This study was designed to verify whether MICALL2 could be a prognostic biomarker to predict kidney renal clear cell carcinoma (KIRC) progression, inflammation, and immune infiltration within tumor microenvironment (TME)." (PMID 35281853, 2022).
MICALL2 also shares sentences with these, for which no sentence is quoted: gastric cancer (5 papers); lung carcinoma (2); non-small cell lung carcinoma (2); colon cancer (1); glioblastoma multiforme (1); lung adenocarcinoma (1); peanut allergy (1); renal clear cell carcinoma (1); sarcoma (1); skin cutaneous melanoma (1).